CRHR1 (corticotropin releasing hormone receptor 1)
Diseases named in the same sentence as CRHR1 in open-access papers (continued):
Sharing a sentence is not in itself a finding about the gene and the disease.
depression (continued). "Some researches showed that increased CRH in chronic stress or depression patients could directly bind to CRHR1 expressed on skin mastocytes and induce degranulation." (PMID 30106230, 2018). "Furthermore, CRHR2 and CRHR1 participated in the co-expression network for healthy controls only, indicating their decreased connectivity with other genes in depression." (PMID 26728011, 2016). "When the diagnosis of depression was not considered, there was a statistically significant association between CRHR1 rs242941 and family history of mental illness; and between GR rs41423247 and regularity of menstrual periods." (PMID 26518448, 2015). "When all subjects were grouped based on family history of mental illness, there was a statistically significant association of CRHR1 rs242941 with family history regardless of depression status (P = 0.043)." (PMID 26518448, 2015). "In addition, two recent studies have demonstrated that CRHR1 SNPs interact with 5-HTTLPR in predicting depression after ELS." (PMID 24596569, 2014). "As CRHR1 may play a significant role in the etiology and treatment of depression, it is suggested that CRHR1 is a relevant candidate gene for MDD." (PMID 22194899, 2011). "According to our hypothesis, an impaired function of CRHR1 would fuel the CRH–NE–CRH circuit, supporting the hyperactivation of the HPA axis with increased secretion of NE and cortisol, the latter especially implicated in metabolic and depressive disorders." (PMID 38927393, 2024). "It is unknown whether the studied SNP-s are functional or they are in linkage disequilibrium with other regions, but it has been previously reported that CRHR1 genotype is related to formation of major depression after stressful life events and could moderate cortisol reactivity to stress." (PMID 32305063, 2020). "A previous study concerning the relationship between depression and pain indicated that a lower dose of CRH injection into rat central amygdaloid nucleus (CeA) could induce the hyperalgesia via CRHR1, which may contribute to explain the “migratory pain” in depression patients." (PMID 30106230, 2018). "In this study, we observed downregulation of CRHR1 in IBS-D, which negatively correlated with pain and stool consistency and with chronic stress and depression." (PMID 33244004, 2020). "At present there are multiple clear examples of such G x E influences on child outcomes; for example, child maltreatment history interaction with 5-HTTLPR, CRHR1, FKBP5, and ADRB2 showing greater vulnerability to depression or PTSD as adults." (PMID 27494520, 2016). "The aim of this study is to examine the single and combined effects of CRH receptor 1 (CRHR1) and BDNF genes in recurrent major depressive disorder (MDD)." (PMID 22194899, 2011). "Our study is innovative as there are no extensive data regarding genetic screening of the CRHR1 gene jointly investigating T2D and depression traits in humans." (PMID 38092990, 2025). "CRHR1 mediates the action of corticotropin-releasing hormone (CRH), one of the most extensively studied systems concerning its potential role in stress and depression." (PMID 34831190, 2021). "In conclusion we could not show an association between depression measurements as assessed by EPDS values during or after pregnancy and candidate haplotypes in the genes FKBP5, NR3C1, and CRHR1." (PMID 24741566, 2014). "The protective effect of the CRHR1 TCA haplotype is only seen in absence of the 5-HTTLPR S allele and only in the absence of the TCA protective haplotype, the S allele increases current depression with moderate levels of child abuse." (PMID 20029939, 2010). "A recent study found that in major depressive disorder and in persistent depressive disorder, specific single nucleotide polymorphisms and haplotypes in genes related to the corticotrophin-releasing hormone (CRHBP, CRHR1) and melanocortins (POMC) predicted the non-responder status." (PMID 31507525, 2019).
alcohol dependence (23 papers, 2012 to 2025). Physical and psychological dependence on alcohol. "Variant CRHR1 haplotypes in adolescents predicted future problem drinking patterns, including binge drinking and lifetime prevalence of intoxication and alcohol dependence." (PMID 29497387, 2018). "Similar to the Crhr1 promoter variants seen in the msP line, human CRHR1 SNPs have been associated with facets of alcohol dependence." (PMID 29497387, 2018). "Together, these findings provide evidence for the involvement of CRHR1 in alcoholism risk through interactions with other genes." (PMID 25802844, 2015). "Interactions between CRHBP and CRHR1 polymorphism have been observed to increase suicide attempts and alcoholism in schizophrenic patients." (PMID 23077729, 2012). "Analysis of a different CRHR1 SNP (rs110402) in schizophrenia patients shows that the T allele interacts with a G allele in a CRHBP SNP (rs3811939) to double the risk of comorbid alcoholism in these patients." (PMID 23077729, 2012). "Considering the comorbidity of alcoholism and ND, as well as the strong genetic correlation between the two behaviors, we hypothesized that variants in CRHR1 are also associated with ND." (PMID 25802844, 2015). "The findings on ND reported here are consistent with the role of CRHR1 in the initiation and maintenance of alcoholism." (PMID 25802844, 2015). "Additional evidence for the relationship between genetic variation in the CrhR1 gene and vulnerability to alcoholism comes from a study in rats." (PMID 23584111, 2012). "In contrast to the extensive research effort to understand the genetic contribution to alcoholism risk, there has been no research directed at understanding the genetic influence of CRHR1 on smoking behavior." (PMID 25802844, 2015). "Collectively, these findings indicate that genetic variations in the Crh and the CrhR1 genes interact with stressful life events to influence age of drinking onset, progression of heavy drinking in adulthood, and general vulnerability to alcohol dependence." (PMID 23584111, 2012). "This suggests that a particular combined genotype of rs110402 in CRHR1 and rs3811939 in CRHBP plays an important role in alcoholism through gene-by-gene interaction." (PMID 25802844, 2015). "Genetic associations of CRF signaling to alcohol phenotypes in humans is not restricted to CRHR1, because several studies link genetic variants in CRHBP, which encodes the CRF-binding protein, to features of alcohol dependence." (PMID 29497387, 2018). "Association analysis revealed that the SNPs in CRHR1 and CRHBP (corticotropin-releasing hormone binding protein) are associated with blood mRNA concentrations in both alcohol-dependent patients and nondependent controls." (PMID 25802844, 2015).
anxiety disorder (15 papers, 2012 to 2025). A category of psychiatric disorders which are characterized by anxious feelings or fear often accompanied by physical symptoms associated with anxiety. "Taken together, current data support a gene-by-environment pathway in which early trauma interacts with the CRHR1 rs110402 A allele to produce limbic hyperreactivity and increase the risk for mood and anxiety disorders." (PMID 41373485, 2025). "Our present results are in agreement with these findings, further corroborating a potential role of Crhr1 in the higher risk of developing anxiety disorders following prenatal trauma and/or being raised by a traumatized mother." (PMID 33758173, 2021). "Previous studies imply that the abnormality of certain genes is associated with anxiety disorders, such as CRHR1, FKBP5, CREB, Egr-1, Glo1, Gsr, AC8, CaMKIV, dystrophin, HTTLPR and COMT Met158." (PMID 22681774, 2012). "Anxiety disorders have previously been linked to differential methylation of specific genes (MAOA, CRHR1, OXTR), and functional magnetic resonance imaging has revealed that the temporal and prefrontal regions of the brain respond differently in patients with anxiety disorders." (PMID 36846567, 2023). "Notably, the CRH receptor (CRHR1) has now been associated with PTSD symptoms, anxiety disorders, and alcohol habitual use in large-scale GWAS studies." (PMID 33057013, 2020). "However, the concatenation of preclinical data suggesting CRF as a crucial factor in the pathogenesis of anxiety disorders has been supported in human genetic studies, in particular with regard to the corticotropin-releasing hormone receptor 1 (CRHR1) gene." (PMID 23717480, 2013). "Interestingly, although not significantly enriched for average p value, the CTNNA2 gene was identified in the million veterans analysis of anxiety disorders, suggesting CTNNA2 is a relevant gene, like CRHR1, that is shared between human anxiety disorders and rhesus monkey infant-IT." (PMID 34035480, 2021). "With our association study in a cohort of pregnant women without further risk factors for depressive or anxiety disorders, we could not show that candidate single nucleotide polymorphisms within the genes FKBP5, NR3C1, and CRHR1 are associated with EPDS values during or after pregnancy." (PMID 24741566, 2014).
psoriasis (10 papers, 2019 to 2025). An autoimmune condition characterized by red, well-delineated plaques with silvery scales that are usually on the extensor surfaces and scalp. "Psoriasis episodes are often preceded by stressful decreased expression of CRHR-1 which was observed in psoriatic epidermis or dermis, whereas increased levels of CRH were found in the serum of patients with psoriasis." (PMID 34513851, 2021).
Obesity (9 papers, 2007 to 2025). Accumulation of substantial excess body fat. "None of the genotyped variants in genes for monogenic obesity reached genome-wide significance in our GWAS, although several variants in CRHR1, CRHR2, MCHR1, MC3R, MC4R and POMC were nominally associated." (PMID 23251661, 2012).
asthma (8 papers, 2006 to 2025). "Genes in this locus, which include MAPT and CRHR1, have previously been associated with pulmonary fibrosis and inhaled corticosteroid response in asthma." (PMID 26423011, 2015). "Polymorphisms that alter response to asthma therapy include Arg16Gly, Gln27Glu, Thr164Ile for β-agonist receptor, polymorphism of glucocorticoid receptor gene, CRHR1 variants and polymorphism of LTC4S, ALOX5." (PMID 21206697, 2010). "Interestingly, variation of Crhr1 was associated with improved function in the asthma patients who were treated with inhaled corticosteroids." (PMID 16533406, 2006).
colitis (8 papers, 2015 to 2025). Inflammation of the colon. "In contrast to the AOM/DSS model that can be affected by the degree of DSS-induced colitis, our data clearly show that Crhr1 deficiency potently inhibits tumorigenicity in the Apcmin/+ mouse model." (PMID 33494263, 2021). "Previously, we have demonstrated that either loss of Crhr1 encoding gene or a pharmacological blockade of CRHR1 confers protective effects in dextran sulfate sodium (DSS)-induced mouse colitis." (PMID 33494263, 2021). "Contrarily, an oncogenic role has been described for the CRHR1/CRH signaling in a colitis associated-cancer mouse model." (PMID 31614860, 2019). "Mice with colitis showed altered stress-associated behaviour, which is associated with colitis-induced alterations of Npy, Npy1r, Crh, Crhr1, Bdnf and Nr3c1 gene expression in distinct regions of the brain." (PMID 26066467, 2015). "In a DSS-induced colitis mouse model, only CRHR1 knockdown decreased microvascular density, via inhibition of VEGF levels, thus suggesting that CRHR1 acts pro-angiogenic, while CRHR2 has anti-angiogenic properties during intestinal inflammation." (PMID 31614860, 2019). "Characteristically, in a DSS induced colitis murine model, CRHR1 knockdown showed decreased intestinal inflammation, while CRHR2 knockdown exerted increased inflammation, thus supporting the pro-inflammatory and anti-inflammatory roles of CRHR1 and CRHR2 respectively in the intestine." (PMID 31614860, 2019). "Previous study showed that CRF pathway activation in the central nervous system in TNBS-induced rat model of colitis which induced colonic hypersensitivity could be blocked by corticotropin-releasing hormone receptor 1 antagonist." (PMID 30420896, 2018). "Interestingly, CRHR1 promotes intestinal inflammation and angiogenesis in an animal model of colitis, but the effects of CRHR1 are reversed by CRHR2 activation." (PMID 28492284, 2017). "CRHR1 agonists such as Ucn1 were shown to exert anti-inflammatory properties in endotoxemic, or TNBS-induced colitis murine models." (PMID 31614860, 2019). "In the hippocampus, colitis did not alter Npy expression, but increased Npy1r and decreased Crhr1 mRNA levels." (PMID 26066467, 2015).
endometriosis (8 papers, 2013 to 2023). The growth of functional endometrial tissue in anatomic sites outside the uterine body. "Post hoc analyses revealed that for CRHR1 mRNA, the endometriosis group treated with antalarmin was significantly higher than the sham (p<0.05) and the endometriosis group treated with vehicle (p<0.05)." (PMID 31935235, 2020). "Our results demonstrate a general deregulation of MC2R as well as CRHR1 in the adrenal glands during endometriosis and administration of antalarmin." (PMID 31935235, 2020). "Our previous report showed that a short-term treatment with antalarmin, a corticotrophin releasing hormone receptor type 1 (CRHR1) antagonist decreases the number and size of endometriotic vesicles in the auto-transplantation rat model of endometriosis." (PMID 31935235, 2020). "By focusing on the expression of the adrenal receptors we can infer adrenal activity under a chronic inflammatory condition such as endometriosis, and consequences after administration of a CRHR1 antagonist." (PMID 31935235, 2020). "We report for the first time that intra adrenal mRNA of key receptors involved in regulating adrenal activity on hormonal synthesis are altered in an animal model of endometriosis and following treatment with a CRHR1 antagonist." (PMID 31935235, 2020). "Data presented herein represent the first line of evidence for the subsequent testing of the CRHR1 antagonist antalarmin or similar compounds for reducing endometriosis." (PMID 30427841, 2018). "The availability of these new antagonists opens significant possibilities for the advancement of testing new CRHR1 compounds in endometriosis." (PMID 30427841, 2018). "We also demonstrated that antalarmin prevented the increase in CRH and CRHR1 mRNA within endometriosis vesicles as compared to vehicle treated rats, and this reduction was long lasting (almost 2 months after treatment stopped)." (PMID 30427841, 2018). "Our data provides the first in-vivo demonstration for use of CRHR1 antagonist for the treatment of endometriosis opening the possibility for further exploring CRH signaling as a treatment target for this debilitating disease." (PMID 30427841, 2018). "Here we present evidence that a short treatment with the CRHR1 antagonist antalarmin was effective in reducing endometriosis with minimal changes in behavior in a rat model." (PMID 30427841, 2018). "CRHR1 mRNA in endometriosis vesicles showed a two-fold increase as compared to normal uterus of sham rats (t = 2.934, d.f. = 6, p<0.05)." (PMID 30427841, 2018). "Our study opens the possibility for additional pre-clinical testing of CRHR1 inhibitors in endometriosis with the eventual translation of our work into the clinical application." (PMID 30427841, 2018). "There are few preclinical studies of CRHR1 antagonists treating endometriosis and bladder disorders; therefore, additional studies must be done before these drugs reach clinical trials for these diseases such as the studies included in this review that demonstrated positive results." (PMID 35275963, 2022). "Therefore, based on our current results, we suggest CRHR1 blockage partially impede the initial development of endometriotic sites since we still observed that about 60% of the implants sites developed into endometriosis vesicles." (PMID 30427841, 2018). "Our aim was to determine if blocking CRHR1 with antalarmin will reduce endometriosis progression." (PMID 30427841, 2018). "We hypothesized that blockade of CRHR1 during the first week after endometriosis induction will decrease endometriosis vesicle establishment and subsequent development." (PMID 30427841, 2018). "A single week of antalarmin treatment, corresponding to an up regulation of CRHR1 within endometriotic vesicles, was effective in reducing endometriosis in the rat model by reducing the number of developed vesicles by 30% and the size of the vesicles that developed by 67%." (PMID 30427841, 2018).